NUP210 (nucleoporin 210)
Description:
Nucleoporin essential for nuclear pore assembly and fusion, nuclear pore spacing, as well as structural integrity.
Synonyms: POM210; KIAA0906; GP210; FLJ22389
Tractability: Antibody: UniProt predicts a signal peptide or a membrane-spanning region. PROTAC: ubiquitination databases record sites on it; its protein half-life has been measured.
Gene: Protein-coding gene on chromosome 3 (13,316,231 to 13,420,322, reverse strand). Ensembl gene ENSG00000132182.
Subcellular location: Nucleus, nuclear pore complex; Nucleus membrane; Endoplasmic reticulum membrane
Pathways (Reactome):
Disease: Defective TPR may confer susceptibility towards thyroid papillary carcinoma (TPC); HCMV Early Events; HCMV Late Events; NEP/NS2 Interacts with the Cellular Export Machinery; NS1 Mediated Effects on Host Pathways; Nuclear import of Rev protein; Rev-mediated nuclear export of HIV RNA; SARS-CoV-2 activates/modulates innate and adaptive immune responses; Transport of Ribonucleoproteins into the Host Nucleus; Viral Messenger RNA Synthesis; Vpr-mediated nuclear import of PICs
Metabolism of RNA: Transport of Mature mRNA Derived from an Intronless Transcript; Transport of Mature mRNA derived from an Intron-Containing Transcript; Transport of the SLBP Dependant Mature mRNA; Transport of the SLBP independent Mature mRNA; snRNP Assembly; tRNA processing in the nucleus
Metabolism of proteins: SUMOylation of DNA damage response and repair proteins; SUMOylation of DNA replication proteins; SUMOylation of RNA binding proteins; SUMOylation of SUMOylation proteins; SUMOylation of chromatin organization proteins; SUMOylation of ubiquitinylation proteins
Metabolism: IP3 and IP4 transport between cytosol and nucleus; IP6 and IP7 transport between cytosol and nucleus; IPs transport between nucleus and cytosol; Regulation of Glucokinase by Glucokinase Regulatory Protein
Cell Cycle: Nuclear Pore Complex (NPC) Disassembly
Cellular responses to stimuli: Regulation of HSF1-mediated heat shock response
Immune System: ISG15 antiviral mechanism
Gene Ontology:
Molecular function: protein binding
Biological process: nucleocytoplasmic transport
Cellular component: membrane; nuclear envelope; nuclear pore; endoplasmic reticulum membrane; nuclear membrane
Genetic constraint (gnomAD): Loss-of-function variants: 147 observed, 188.62 expected, observed/expected ratio (o/e) 0.78, 90% interval 0.68 to 0.89. The upper end of that interval is the gene's LOEUF score, 0.89, which puts it in group 3 of 6, group 1 being the genes least tolerant of losing a copy. Missense variants: 2,300 observed, 2,528.5 expected, observed/expected ratio (o/e) 0.91, 90% interval 0.88 to 0.94. Synonymous variants: 1,064 observed, 1,059.5 expected, observed/expected ratio (o/e) 1, 90% interval 0.95 to 1.06.
Homologues: Orthologues: chimpanzee NUP210 (99% identical), macaque NUP210 (98% identical), dog NUP210 (87% identical), mouse Nup210 (84% identical), rat Nup210 (84% identical), pig NUP210 (83% identical), rabbit NUP210 (83% identical), guinea pig NUP210 (82% identical), zebrafish nup210 (60% identical), Caenorhabditis elegans npp-12 (25% identical), Drosophila melanogaster Gp210 (24% identical). Paralogues in human: NUP210L (45% identical).